ALB (albumin)
Diseases named in the same sentence as ALB in open-access papers (continued):
Sharing a sentence is not in itself a finding about the gene and the disease.
cancer (continued). "Firstly, the primary findings of this study focus on the relationship between albumin levels and overall cancer mortality, which can be applied to various aggressive and less aggressive cancers, but not to specific cancer types." (PMID 38500655, 2024). "Therefore, while low albumin and PNI are established markers for poor prognosis in general cancer populations, their prognostic value in long-term cancer survivors with LLL remains uncertain and warrants further investigation." (PMID 39529928, 2024). "In another study, integrin αvβ3, a protein that is overexpressed in many types of cancer cells, was targeted with cyclic arginine-glycine-aspartate (cRGD) by using maleimide-functionalized closo-dodecaborate albumin conjugate (MID-AC) with albumin." (PMID 38961887, 2024). "Therefore, the novel index, albumin-to-alkaline phosphatase ratio (AAPR), is believed to serve as a valuable prognostic indicator in cancer patients." (PMID 38216656, 2024). "After it was understood that the immune and nutritional status had an effect on cancer prognosis, various parameters and indices reflecting the immune status (CRP, lymphocyte, albumin, neutrophil, NLR, PLR, MLR, pan-immune ınflammatıon value (PIV)) have been the subject of studies." (PMID 38777931, 2024). "Although a high C-reactive protein-to-albumin ratio (CAR) is believed to increase mortality risk, the association between the physical activity (PA), CAR, and mortality among cancer survivors has not been investigated." (PMID 39358685, 2024). "Therefore, we investigated the relationship between ALB and ALP levels in a representative sample of patients with malignancies using the 2011 to 2018 National Health and Nutrition Examination Survey (NHANES) database." (PMID 38552093, 2024). "Kaplan-Meier curves demonstrated that patients with albumin levels ≤ 4.2 g/dL exhibited lower survival rates compared to those with levels > 4.2 g/dL, irrespective of cancer aggressiveness." (PMID 38500655, 2024). "Pretreatment prealbumin and albumin levels were slightly lower in patients with infectious complications during cancer treatment compared with patients without complications." (PMID 39619813, 2024). "The combination of even modest reductions in albumin, reflective of chronic inflammation, combined with even modest elevations of markers of acute inflammation such as CRP and neutrophils, appear to be important predictors of survival in patients with cancer." (PMID 38404120, 2024). "Albumin-based indices, fibrinogen-albumin ratio (FAR), neutrophil-lymphocyte ratio (NLR), platelet-lymphocyte ratio (PLR), and neutrophil, lymphocyte, platelet percentages alone are used to predict prognosis in several cancer types." (PMID 39061000, 2024). "Recent research has confirmed that folate-bovine serum albumin-coated ethoniosomes of pterostilbene allowed specific targeting of cancer tissues overexpressing folate receptors rather than healthy tissues." (PMID 39026680, 2024). "Our group has previously explored the prognostic role of several biomarkers of systemic inflammation, including c‐Reactive Protein (CRP), albumin, white cell count (WCC) neutrophil count (NC), in patients presenting with malignancy of undefined primary origin MUO or CUP to a single cancer centre." (PMID 38404120, 2024). "To evaluate predictors and their association with overall survival from the start of last-line chemotherapy until death, we explored models within PAN and GI groups based on baseline PS, albumin, CRP, and mGPS in a basic model (adjustments for age, sex, hospital size, and cancer diagnosis)." (PMID 39330032, 2024). "In recent years, the Hemoglobin, Albumin, Lymphocyte, Platelet Score (HALP) has surfaced in the literature as a novel prognostic indicator utilized to predict various clinical outcomes across different types of cancers." (PMID 39372874, 2024).
cancer (continued). "Combining serum albumin and fibrinogen levels, FAR provides a reliable measure of systemic inflammation and is valuable in predicting outcomes in various conditions, including cardiovascular diseases and cancer." (PMID 39744304, 2024). "In terms of clinical research, future studies should refine the inclusion criteria, expand the sample size, focus on exploring the relationship between albumin and the prognosis of specific cancer types, particularly the nonlinear relationship." (PMID 38500655, 2024). "Furthermore, nutritional factors have been found to significantly influence cancer prognosis, as evidenced by the fibrinogen-to-albumin ratio (FAR), C-reactive protein albumin ratio (CAR), and prognostic nutritional index (PNI)." (PMID 39301556, 2024). "Although the majority of these factors have been proven correlated with prognosis among cancer patients, including CRP, WBC, neutrophil‐to‐lymphocyte ratio, albumin, alkaline phosphatase, hemoglobin, and ECOG, this is the first study that shows their combined effect when incorporated into one model." (PMID 35871390, 2023). "Similarly, several previous studies also explored the usefulness of other albumin-related prognostic markers, including PNI, ALI, and AGR, for the prognosis of cancer patients." (PMID 36875131, 2023). "Hence, we have used albumin to conjugate chlorogenic acid (CGA) and to synthesize green albumin CGA NPs for evaluating its use in anti-microbial and anti-cancer applications." (PMID 37176983, 2023). "Based on the unique properties of human serum albumin (HSA), we have developed a novel single protein encapsulation (SPE) technology to formulate cancer therapeutics for improving their pharmacokinetics (PK) and antitumor efficacy and reducing their side effects." (PMID 38072965, 2023). "The predictive ability for patients with advanced cancers might be improved by combining CRP with other parameters, such as plasma albumin and NLR." (PMID 37009523, 2023). "In numerous types of cancer, the GNRI, which is comprised of a patient's serum albumin level, height, and weight, has been demonstrated to be a more accurate indicator of nutritional status than BMI and serum albumin." (PMID 37380982, 2023). "In this study, we synthesized flexible hollow human serum albumin (HHSA), which can enhance drug delivery and cellular uptake, and loaded in photosensitizer Chlorin e6 (Ce6) and chemotherapeutic drug Doxorubicin (DOX) for synergistic cancer therapy." (PMID 36798745, 2023). "Therefore, the cumulative effect of ALB and GLB can provide effective prognostic value for cancer patients." (PMID 37828259, 2023). "Moreover, albumin can engage with other ECM proteins, such as laminin and fibronectin, contributing to the inhibition of cancer cell invasion." (PMID 37987317, 2023). "Overall, nanomedicine has shown promising results in terms of bench-to-bedside research for cancer therapy and these innovations were responsible for early FDA approvals for Doxorubicin-loaded liposome (Doxil®) and Paclitaxel-loaded albumin nanoparticles (Abraxane®) in early 1990s." (PMID 37152753, 2023). "The neutrophil-to-albumin ratio (NPAR) is a cost-effective, readily available biomarker of inflammation used to assess cancer and cardiovascular disease prognosis, and it may be of predictive value in NAFLD." (PMID 37111111, 2023). "Sex differences in albumin levels and inflammatory markers have been found in other medical conditions too, but, to our knowledge, it has not been studied in patients with cancer." (PMID 37880704, 2023). "ALB and GLB are two important components of systemic inflammation, and the combination of these two markers (AGR) has been reported to be significant and validated in several types of cancers." (PMID 37081512, 2023).
cancer (continued). "BMI: body mass index; CA: cancer; G-CSF: granulocyte colony-stimulating factor; BSA: blood serum albumin; ECOG: Eastern Cooperative Oncology Group performance status; eGFR: estimated glomerular filtration rate; CEA: carcinoembryonic antigen; LDH: lactate dehydrogenase." (PMID 36819321, 2023). "Although ALB and GLB can be used to predict the clinical outcomes of patients with cancer 50, 51, the measurement of a single indicator may be affected by host factors, such as body fluid changes, hepatic dysfunction, and acute infection or inflammation." (PMID 36741261, 2023). "Based on this study, mean level of Serum albumin, TP and Hgb were deranged in malnourished as compared to nourished adult patients with cancer." (PMID 36869395, 2023). "The finding is supported with study done in Iran serum albumin level is significantly lower in GI patients with cancer than non-GI patients with cancer." (PMID 36869395, 2023). "Hence, the correlation between TMMV and established predictive biomarkers of cancer cachexia, including IL-1, TNF-alpha, IL-6, CRP, and serum albumin, warrants investigation." (PMID 37959329, 2023). "Specifically, the variables in group 1 included gender, pulse, systolic pressure, leucocyte count, neutrophils count, lymphocyte count, neutrophil-to-lymphocyte ratio (NLR), c-reactive protein (CRP), procalcitonin(pct), albumin, urea nitrogen (BUN), D-dimer and cancer(p < 0.05)." (PMID 37528213, 2023). "The expression of ALB and TP, recognized as relevant proteins for monitoring nutritional status, was lower in the GST group than in the other two groups, which is consistent with other cancers." (PMID 37833709, 2023). "Additionally, the serum albumin, lymphocytes, NLR, and SIS were identified as independent predictors for cancer-related death." (PMID 38156280, 2023). "The results indicate that conjugating the PD-L1 aptamer to albumin may serve as a promising strategy to improve the in vivo functionality of the aptamer and that BSA-Apt may have application potential in cancer immunotherapy." (PMID 35268583, 2022). "Therefore, the combination of them, LDH to serum albumin ratio (LAR), was recommended to be a good prognostic ratio for patients with cancers 16-18." (PMID 35813299, 2022). "Researchers proposed to develop two Cu (II) complexes based on the His242 residue of the IIA subdomain of the human serum albumin (HSA) carrier (13 and 14) to improve the delivery efficiency, anti-cancer activity and selectivity of anti-cancer metal preparations in vivo." (PMID 36238553, 2022). "The modified Glasgow outcome scale (mGPS) and C-reactive protein-to-albumin ratio (CAR), are based on the two important acute phase proteins in SIR, namely C-reactive protein (CRP) and albumin, and are related to the prognosis of cancer patients." (PMID 35606690, 2022). "ΔS-Cys-Albumin was measured at 9 to 11 different time points per exposure temperature (23 °C, 4 °C, or −20 °C) in K2EDTA plasma and serum aliquots from 12 GI cancer patients and 12 cancer-free donors." (PMID 36182099, 2022). "Thus, a commercial PTX-loaded albumin formulation, Abraxane®, was approved by the U.S. FDA to treat some cancers." (PMID 35203695, 2022). "In this study, 2 albumin binder–conjugated FAPIs, denoted as TEFAPI-06 and TEFAPI-07, were developed to optimize the pharmacokinetics of current FAPI radiopharmaceuticals for cancer radiotherapy." (PMID 34593598, 2022). "Recently, a bovine serum albumin (BSA)-based hydrogel, containing epichlorohydrin as a crosslinker, has been shown to be a suitable drug scaffold providing sustained release of doxorubicin to cancer cells." (PMID 35745747, 2022). "A study on ALB and cancer found that the serum ALB level of cancer subjects was significantly lower than that of non-cancer subjects." (PMID 36290873, 2022).
cancer (continued). "Therefore, albumin levels could be a biologically plausible biomarker with the potential to reflect both the nutritional status and inflammatory pressure on patients with cancer and decreased levels of albumin could reflect a more advanced cancer stage and a more dismal prognosis." (PMID 36533070, 2022). "Using a large dataset, we showed that the utility of pretreatment serum albumin is not confined to one or two cancer types but is a broad indicator of ICB outcome." (PMID 35393553, 2022). "Information on the prognostic significance of fibrinogen and albumin individually or in combination in cancer is still not sufficient." (PMID 36496365, 2022). "The SIS combines albumin and LMR values and has been noted to be superior to other blood-borne markers like the NLR, modified Glasgow Prognostic Score, and lymphocyte C-reactive protein score for patients with cancer." (PMID 36338660, 2022). "In patients with GPS 1, those with low serum albumin and CRP levels may be undernutrition related with cancer, while those with high serum albumin and CRP levels may be pre-cachexic." (PMID 34519976, 2022). "Most cancer patients were not undergoing chemotherapy at the time of blood collection, and those that were did not have different ΔS-Cys-Albumin values." (PMID 36182099, 2022). "Immunoglobulins and highly abundant urinary proteins (serum albumin, uromodulin, serotransferrin) were excluded due to their high abundance in biological samples and the lack of specificity for cancer, resulting in 170 proteins." (PMID 35454907, 2022). "The effects of serum albumin on clinical response to ICB therapy across diverse cancer types are not fully elucidated." (PMID 35393553, 2022). "GPS, based on CRP and ALB has been widely adopted as a systemic inflammatory and nutritional index, which indicated as a prognostic score not only for postoperative survival in ESCC but also for survival in various cancers." (PMID 35300627, 2022). "The Glasgow Prognostic Score, an inflammation-based cancer-prognostic marker composed of serum elevation of CRP and decrease in albumin concentration, predicts patients with systemic inflammation as part of cancer cachexia and has been shown to have independent prognostic value." (PMID 36158184, 2022). "The decrease in hemoglobin and albumin levels and the increase in C-reactive protein (CRP) levels observed in the BTC group may indicate carcinoma status." (PMID 36358797, 2022). "The albumin-to-globulin ratio (AGR) was an independent prognostic factor for both overall survival (OS) and cancer-specific survival (CSS) for patients with localized or locally advanced clear cell renal cell carcinoma (CCRCC), and patients with low AGR had poorer OS and CSS." (PMID 33859986, 2021). "PNI, a well-designed marker composed of albumin and lymphocytes that assesses the immunological and nutritional states in humans, is recognized as an effective negative prognostic factor in cancers." (PMID 33718126, 2021). "The prognostic value of the C-reactive protein to albumin ratio (CAR) among older adults with cancer is not known." (PMID 34830936, 2021). "Albumin is a nutritional marker that identifies poor nutritional status in cancer patients and is a negative acute-phase reactant that decreases in inflammatory states indicating a compromised immune system." (PMID 34885052, 2021). "As a host response to cancer-mediated by cytokines, systemic inflammation often occurs with an activation of the hepatic acute-phase protein response, which can lead to increased levels of C-reactive protein (CRP) and decreased levels of albumin." (PMID 34830936, 2021). "This study provides a simple strategy to form albumin nanoparticles, which could enhance phototherapy of NIR photosensitizers by both enhanced PDT and PTT for clinical cancer treatment." (PMID 33407570, 2021).
cancer (continued). "Although there have been many studies on cancers and inflammatory diseases with inflammatory cytokines, fibrinogen, CRP, albumin, and hematological indexes as inflammatory markers, these parameters are limited in the differential diagnosis of IGM and early onset BC." (PMID 34356979, 2021). "GPS is also useful for advanced cancer patients in palliative care (palliative care unit, palliative care team in general wards, home palliative care), and 71% of the patients had CRP ≥1.0 mg/dL and albumin <3.5 g/dL (=GPS 2)." (PMID 33808957, 2021). "Albumin (ALB) and globulin (GLB), the crucial parts of human serum proteins, have been considered as independent prognostic predictors for patients among kinds of cancers due to the regulation of inflammatory cytokines." (PMID 34616677, 2021). "In this study, the predictive ability of AGR for the prognosis of patients with cancer cachexia is higher than that of ALB, GLB, or TB alone; and the results of subgroup analysis show that AGR can further distinguish the prognosis of normal ALB group." (PMID 34568033, 2021). "Hemoglobin, albumin, lymphocyte and platelet (HALP) score, consisting of four laboratory markers in both nutritional and inflammatory status, including HALP is recently proposed to predict the prognosis in patients with several types of cancers." (PMID 33974528, 2021). "Given our data, we hypothesize that low albumin and high LDH and CRP serve as markers of cancer-related systemic inflammation and cachexia, resulting also in a greater hypercoagulable state in these patients." (PMID 34521927, 2021). "The CRP albumin ratio has also been shown predictive of mortality in patients without cancer for example in patients having systemic lupus with serious community-acquired infection or in critically ill patients." (PMID 34944774, 2021). "Similarly, there was also a statistically significant difference in PG-SGA scores and albumin levels between the intervention and control group among patients at stage III–IV and both types of cancer (p < 0.05)." (PMID 34356221, 2021). "Previous studies have examined the prognostic significance of inflammatory response markers, including neutrophil-to-lymphocyte ratio (NLR), C-reactive protein (CRP)-to-albumin ratio (CAR), platelet-to-lymphocyte ratio (PLR), and albumin-to-globulin ratio (AGR), for various cancers." (PMID 34115873, 2021). "Furthermore, in a random survival forest analysis of clinical factors and laboratory variables in older patients with various types of cancer, we showed that the CRP/albumin ratio made the largest contribution to the prediction of one-year mortality." (PMID 34944774, 2021). "GPS is a scoring system that combines CRP and albumin, and is a prognostic score for cancer patients independent of the stage of the disease." (PMID 33808957, 2021). "This discussion will focus on exogenous albumin-based cancer therapeutics since in situ binders are not suitable for IP administration." (PMID 31858848, 2020). "Herein, a novel phototheranostic nanocomplex that is self-assembled from bovine serum albumin (BSA) and indocyanine green (ICG) is developed for enhanced near-infrared (NIR) fluorescence imaging, which benefits the guidance on in vivo cancer photothermal therapy (PTT)." (PMID 32183838, 2020). "Potential SIR-related biomarkers in cancer patients include as CRP, NLR, PLR, albumin and GPS." (PMID 32974174, 2020). "Recent studies have indicated that CRP-to-albumin ratio (CAR), also created on serum albumin levels and CRP levels, is a valuable prognosticator in various cancers and may provide more accurate prognostic prediction than other indicators." (PMID 32587804, 2020). "Serum PD‐L1 levels were significantly correlated with neutrophil counts and CRP, albumin, and SCC‐Ag levels; in addition, correlations were observed among serum PD‐L1 level, advanced‐stage cancer, and lymphocyte counts (statistical significance notwithstanding)." (PMID 31865635, 2020).